RPP30 (ribonuclease P/MRP subunit p30)
Description:
Component of ribonuclease P, a ribonucleoprotein complex that generates mature tRNA molecules by cleaving their 5'-ends. Also a component of the MRP ribonuclease complex, which cleaves pre-rRNA sequences.
Synonyms: TSG15
Tractability: PROTAC: ubiquitination databases record sites on it; its protein half-life has been measured.
Gene: Protein-coding gene on chromosome 10 (90,871,487 to 90,908,553, forward strand). Ensembl gene ENSG00000148688.
Subcellular location: Nucleus, nucleolus
Subcellular location (Human Protein Atlas): Nucleoli; Nucleoplasm; Cytosol; Microtubule ends
Pathways (Reactome):
Metabolism of RNA: Major pathway of rRNA processing in the nucleolus and cytosol; tRNA processing in the nucleus
Gene Ontology:
Molecular function: protein binding; ribonuclease P activity; ribonuclease P RNA binding; RNA binding
Biological process: tRNA 5'-leader removal; RNA processing; tRNA processing
Cellular component: multimeric ribonuclease P complex; nucleolar ribonuclease P complex; ribonuclease MRP complex; nucleoplasm; nucleus; nucleolus
Genetic constraint (gnomAD): Loss-of-function variants: 12 observed, 14.18 expected, observed/expected ratio (o/e) 0.85, 90% interval 0.54 to 1.37. The upper end of that interval is the gene's LOEUF score, 1.37, which puts it in group 5 of 6, group 1 being the genes least tolerant of losing a copy. Missense variants: 172 observed, 173.98 expected, observed/expected ratio (o/e) 0.99, 90% interval 0.87 to 1.12. Synonymous variants: 77 observed, 68.77 expected, observed/expected ratio (o/e) 1.12, 90% interval 0.93 to 1.35.
Homologues: Orthologues: chimpanzee RPP30 (98% identical), macaque RPP30 (98% identical), dog RPP30 (94% identical), guinea pig RPP30 (92% identical), rabbit RPP30 (91% identical), rat Rpp30 (91% identical), mouse Rpp30 (90% identical), pig RPP30 (83% identical), tropical clawed frog rpp30 (70% identical), zebrafish rpp30 (60% identical), Drosophila melanogaster Rpp30 (33% identical), Caenorhabditis elegans H35B03.2 (28% identical).
Diseases named in the same sentence as RPP30 in open-access papers:
RPP30 is named in the same sentence as 20 diseases in open-access papers, as found by Europe PMC text mining. Sharing a sentence is not in itself a finding about the gene and the disease. The quoted sentences say what the papers report.
glioblastoma (4 papers, 2020 to 2024). The most malignant astrocytic tumor (WHO grade IV). "As other components of RNase P or MRP, both RPP25 and RPP30 were reported as reliable prognostic risk factors for glioblastoma multiforme and also have been reported to promote the proliferation, migration, invasion, and cell cycle program of cervical cancer cells." (PMID 36091104, 2022). "A new study found that RPP30 may be a transcriptional regulator in glioblastoma (GBM) and the decreased RPP30 expression in elderly people could be a risk factor for GBM." (PMID 36313673, 2022). "Furthermore, both RPP25 and RPP30, another component of RNase P and MRP, were reported as reliable prognostic risk factors for glioblastoma multiforme." (PMID 36091104, 2022). "Additionally, RPP30 was reportedly highly correlated with glioblastoma (GBM); low expression of RPP30 may be a trigger for GBM, serving as an independent prognostic factor for GBM." (PMID 38862431, 2024).
COVID-19 (3 papers, 2022 to 2023). A disease caused by infection with severe acute respiratory syndrome coronavirus 2. "The vast majority of COVID-19 tests are currently targeting the human RNase P gene (denoted RPP30 or h-RP) as a positive control to monitor RNA extraction and its quality to be reverse transcribed for its subsequent PCR amplification." (PMID 35083313, 2022). "On the other hand, the CDC COVID-19 assay can qualitatively detect the N gene for the new SARS-CoV-2 and the RPP30 gene, which can confirm the validity of all test reactions." (PMID 36547078, 2022). "We therefore measured the expression of IFI6 and GBP5 (relative to the reference gene RPP30) using qPCR assays on swabs from a new cohort of patients with (n = 72) or without (n = 72) COVID-19 (Data Set S3)." (PMID 36507688, 2023).
glioma (3 papers, 2020 to 2023). A benign or malignant brain and spinal cord tumor that arises from glial cells (astrocytes, oligodendrocytes, ependymal cells). "In conclusion, we found that RPP30, which is expressed less with age, maybe one of the pathogenic factors leading glioma, and RPP30-targeted therapy could potentially be used for clinical treatment of GBM patients." (PMID 32702667, 2020). "Using a previously validated ratio that controls for genomic DNA, the HML-2 ratio was significantly higher in the CSF of patients with glioma compared with that of patients with epilepsy (HML-2/RPP30)." (PMID 37395282, 2023). "The expression and function of RPP30 in gliomas has been previously reported." (PMID 35928448, 2022). "Herein, we reported for the first time an analysis of the biological functions of RPP30 in glioma." (PMID 32702667, 2020). "Therefore, we speculated that RPP30 may play an important role in glioma with potential as a novel therapeutic target." (PMID 32702667, 2020).
gastric cancer (2 papers, 2022). A primary or metastatic malignant neoplasm involving the stomach. "used TGCA RNA-seq to explore the role of RPP30 expression in gastric cancer." (PMID 36313673, 2022).
systemic sclerosis (2 papers, 2021 to 2022). A chronic disorder, possibly autoimmune, marked by excessive production of collagen which results in hardening and thickening of body tissues. "Interestingly, hRpp38 has been identified as the main component, along with Pop1, Rpp25 and Rpp30, of the Th/To autoantigen present in the sera of patients suffering from systemic sclerosis scleroderma (SSc)." (PMID 34638646, 2021).
anemia (1 paper, 2023). A reduction in the number of red blood cells, the amount of hemoglobin, and/or the volume of packed red blood cells. "TBP, MAPK1, and RPP30 are the most stable genes that are uninterrupted by anemia, OIR and EPO administration." (PMID 37098032, 2023). "Expression of Rpp30 is the least affected by experimental conditions of oxygen induced retinopathy, phlebotomy induced anemia and erythropoietin administration at both timepoints of P14.5 and P20." (PMID 37098032, 2023).
autoimmune disease (1 paper, 2022). A disorder resulting from loss of function or tissue destruction of an organ or multiple organs, arising from humoral or cellular immune responses of the individual to their own tissue constituents. "RPP30 is indirectly related to some diseases, including lung diseases and pulmonary hypertension, secondary to autoimmune diseases." (PMID 36313673, 2022).
endometriosis (1 paper, 2025). The growth of functional endometrial tissue in anatomic sites outside the uterine body. "On average, there are 3.9 times as many copies of the RPP30 gene in the endometriosis group as there are in the control group." (PMID 39858463, 2025).
lung diseases (1 paper, 2022). "In addition, people with positive anti-RPP30 antibodies have a lower risk of tendon friction rubs and cancer, but more likely to have severe lung diseases and pulmonary hypertension." (PMID 36313673, 2022).
Ogden syndrome (1 paper, 2025). Ogden syndrome is a rare, genetic progeroid syndrome characterized by a variable phenotype including postnatal growth delay, severe global developmental delay, hypotonia, non-specific dysmorphic facies with aged appearance and cryptorchidism, as well as cardiac arrthymias and skeletal anomalies. "Combined analyses of Ogden syndrome cellular models and HeLa cancer models identified a subset of common N-terminally acetylated proteins, including GCN1, ELOA, PPIA, RPL13A, RPP30, and SAE1." (PMID 40558489, 2025).
pancreatic adenocarcinoma (1 paper, 2022). "RPP30 expression was significantly different in tumor tissues (higher) and non-tumor tissues in diffuse large B-cell lymphoma, pancreatic adenocarcinoma (PAAD) and thymoma (THYM)." (PMID 36313673, 2022).
Respiratory tract infection (1 paper, 2024). An infection of the upper or lower respiratory tract. "Therefore, RPP30 exhibits a positive correlation with nucleic acid segments and can be used as an internal control for sampling quality in individuals with respiratory tract infection." (PMID 39382280, 2024).
tumor (8 papers, 2020 to 2025). "In comparison to the low expression of RPP30, the high expression of RPP30 was associated with increased Th2 cell infiltration in the tumor microenvironment (p < 0.001)." (PMID 35928448, 2022). "Although RPP30 is associated with appellate disease, the expression of RPP30 in normal tissues and most tumor cells is stable." (PMID 36313673, 2022). "Compared with non-tumor brain samples, we found a loss of post-translational protein modification of RPP30 in GBM." (PMID 32702667, 2020). "In-depth studies have found that RPP30 expression affected the post-transcriptional modification of tumor pathway genes, which may be one of the causes of primary GBM." (PMID 32702667, 2020). "This study showed that RPP30 was related to RNA and post-transcriptional modification in non-tumor tissues, and RNA modification in GBM." (PMID 36313673, 2022). "RPP30 is used as an internal reference gene to determine the best effective drug concentration for tumor treatment." (PMID 36313673, 2022). "There was a significant statistical difference in RPP30 expression between tumor and paracancerous normal tissues (p < 0.001), and a higher expression of RPP30 was observed in tumor tissues." (PMID 35928448, 2022). "In contrast, the activation of tumor-related pathways and proliferation ability of HA cells were impaired by the over-expressed RPP30." (PMID 32702667, 2020). "Univariate analysis also revealed that T stage (p = 0.011), N stage (p = 0.002), M stage (p = 0.004), pathological stage (p < 0.001), primary therapy outcome (p < 0.001), residual tumor (p < 0.001), age (p = 0.005), and RPP30 expression (p = 0.012) were significantly correlated with OS." (PMID 35928448, 2022). "Our study demonstrated that high RPP30 expression was significantly correlated with tumor progression and poor survival in GC, which might promote tumorigenesis and angiogenesis via tRNA dysregulation." (PMID 35928448, 2022). "Thus, the use of RPP30 as an internal reference gene for many applications, including detection of pathogens, calculation of the number of tumor cells, diagnosis of tumors, and some childhood diseases are discussed." (PMID 36313673, 2022). "We found that whereas RPP30 in primary GBM was primarily associated with translation-related functions, it was associated with protein ubiquitination and folding functions in non-tumor brain samples." (PMID 32702667, 2020). "Further, we measured the relative expression of RPP30 in non-tumor and GBM samples via qRT-PCR." (PMID 32702667, 2020). "However, we also found that the specific post-transcriptional modifications made by RPP30 were different in tumor and non-tumor brain samples." (PMID 32702667, 2020). "We conducted gene ontology (GO) term enrichment analyses to determine the function of RPP30 in primary GBM and non-tumor brain samples." (PMID 32702667, 2020). "According to previously published results from GISTIC analysis of 10,844 tumor samples, RPP30 shows no significant copy number alterations and has therefore been widely adopted as a reliable reference gene in copy number studies." (PMID 40707918, 2025). "The patient-based analysis identified one additional significant gene, ZNF845 (Padj = 2.6 × 10−2), whereas the tumor-based analysis identified four, TNRC6B (Padj = 2.9 × 10−4), ZNF780B (Padj = 4.2 × 10−2), RPP30 (Padj = 6.4 × 10−2), and CASQ1 (Padj = 8.7 × 10−2)." (PMID 35922826, 2022). "To apply this ddPCR-based method to clinical samples, we measured the amount of intrahepatic cccDNA and RPP30 in tumor and non-tumor tissues from five HBV-related HCC patients using the ddPCR assay." (PMID 35136096, 2022). "Our study found that RPP30 was mainly involved in the post-translational modification in both tumor and non-tumor samples." (PMID 32702667, 2020). "Consistent with previous research findings, we found that RPP30 was involved in the modification of RNA, not DNA, in both tumor and non-tumor samples." (PMID 32702667, 2020).
tumor (continued). "Since there is no anti-RPP30 antibody available for immunohistochemistry, we measured the relative expression of RPP30 in non-tumor and GBM brain samples via qRT-PCR." (PMID 32702667, 2020). "Surprisingly, we found that RPP30 was closely related to protein modification in non-tumor brain samples, but not in primary GBM samples in both the CGGA and TCGA databases." (PMID 32702667, 2020). "However, the post-transcriptional modifications carried out by RPP30 were different in primary GBM and non-tumor brain samples." (PMID 32702667, 2020).
cancer (7 papers, 2019 to 2025). A tumor composed of atypical neoplastic, often pleomorphic cells that invade other tissues. "Indeed, as a conserved RNase P protein subunit, Rpp30 has been found to play essential roles, and dysregulation of Rpp30 has been linked to diseases, such as female sterility in Drosophila and cancers in humans." (PMID 37884868, 2023). "Although RPP30 is a housekeeping gene and its encoding protein is a key subunit that maintains basic life activities, it is rarely reported to be associated with human diseases, and is overexpressed only in a few patients with cancer." (PMID 36313673, 2022). "In addition, we found that the downregulation of RPP30 can increase phosphorylation/activation of cancer pathway-associated proteins in vitro." (PMID 32702667, 2020). "TCGA copy-number data analysis indicates no significant amplification was observed in the gene region of RPP30 in many cancer types." (PMID 40621475, 2025). "Meanwhile, the expression level of RPP30 was significantly correlated with the expression of genes in the cancer-related pathways (Pathway in cancer, WNT Pathway, MAPK Pathway, and WNT Pathway) in both CGGA and TCGA databases." (PMID 32702667, 2020). "Functional enrichment analysis of the proteins that receive post-transcriptional modifications from RPP30 revealed that those proteins were mainly involved in the activation of cancer signaling pathways." (PMID 32702667, 2020). "In addition to transcriptional modification, RPP30 was positively correlated with the WNT signaling pathway (pro-cancer) and negatively correlated with several drug metabolism pathways (cytochrome p450 and ABC transporters)." (PMID 32702667, 2020). "RPP30 affected protein expression of cancer pathways by performing RNA modifications." (PMID 32702667, 2020). "Correlation analysis of RPP30 expression levels with gene expression in cancer-related pathways, such as cancer, Wnt, and mitogen-activated protein kinase pathways in the Chinese Glioma Genome Atlas and The Cancer Genome Atlas databases show significant correlation." (PMID 36313673, 2022). "RPP30 affects tRNA processing, transcription replication, DNA repair, and replication fork stalling; regulates protein expression; enriches cancer-related pathways, leading to tumorigenesis; and eventually promotes the proliferation, metastasis, and invasiveness of cancer cells." (PMID 35928448, 2022). "RPP30 could regulate tRNA modification, transcriptional replication, DNA repair, replication fork stagnation, and protein expression, which are correlated with cancer cell proliferation." (PMID 36313673, 2022). "In addition, the copy number of RPP30 and those of other reference genes in CAR-T cells across different cancer types are comparable." (PMID 40621475, 2025). "RPP30 regulates protein expression in GBM by affecting post-transcriptional modification of proteins and functional accumulation of these proteins indicates that these proteins are mainly involved in the activation of cancer signaling pathways." (PMID 36313673, 2022).
infection (1 paper, 2017). The state of being infected such as from the introduction of a foreign agent such as serum, vaccine, antigenic substance or organism. "Infection load and the concentration of RPP30 endogenous control DNA were quantified." (PMID 28966918, 2017).
RPP30 also shares sentences with these, for which no sentence is quoted: epilepsy (1 paper); HTLV infection (1); pulmonary hypertension (1); retinopathy (1); severe combined immunodeficiency (1).